GLYATL2 (glycine-N-acyltransferase like 2)
Description:
Mitochondrial acyltransferase which transfers the acyl group to the N-terminus of glycine. Conjugates numerous substrates, such as arachidonoyl-CoA and saturated medium and long-chain acyl-CoAs ranging from chain-length C8:0-CoA to C18:0-CoA, to form a variety of N-acylglycines. Shows a preference for monounsaturated fatty acid oleoyl-CoA (C18:1-CoA) as an acyl donor. Does not exhibit any activity toward C22:6-CoA and chenodeoxycholoyl-CoA, nor toward serine or alanine.
Synonyms: BXMAS2-10; MGC24009; GATF-B
Tractability: No criterion of Open Targets' tractability assessment is met for any kind of drug.
Gene: Protein-coding gene on chromosome 11 (58,834,065 to 58,904,215, reverse strand). Ensembl gene ENSG00000156689.
Subcellular location: Endoplasmic reticulum
Subcellular location (Human Protein Atlas): Mitochondria
Pathways (Reactome):
Metabolism: Conjugation of benzoate with glycine; Conjugation of carboxylic acids; Conjugation of salicylate with glycine
Drug ADME: Aspirin ADME
Gene Ontology:
Molecular function: glycine N-acyltransferase activity
Biological process: long-chain fatty acid catabolic process; medium-chain fatty acid catabolic process; monounsaturated fatty acid catabolic process
Cellular component: endoplasmic reticulum; mitochondrion
Genetic constraint (gnomAD): Loss-of-function variants: 19 observed, 16.76 expected, observed/expected ratio (o/e) 1.13, 90% interval 0.79 to 1.65. The upper end of that interval is the gene's LOEUF score, 1.65, which puts it in group 6 of 6, group 1 being the genes least tolerant of losing a copy. Missense variants: 317 observed, 305.72 expected, observed/expected ratio (o/e) 1.04, 90% interval 0.94 to 1.14. Synonymous variants: 104 observed, 104.8 expected, observed/expected ratio (o/e) 0.99, 90% interval 0.85 to 1.17.
Homologues: Orthologues: chimpanzee GLYATL2 (99% identical), pig GLYATL2 (64% identical), tropical clawed frog glyatl2 (29% identical), zebrafish si:ch73-106k19.2 (23% identical), zebrafish si:dkey-76k16.6 (23% identical), Caenorhabditis elegans T10B10.4 (18% identical), Caenorhabditis elegans ZK185.3 (18% identical), zebrafish si:dkey-76k16.5 (18% identical), Caenorhabditis elegans F43H9.4 (13% identical). Paralogues in human: GLYATL1 (50% identical), GLYATL1B (49% identical), GLYAT (41% identical), GLYATL3 (34% identical).
Diseases named in the same sentence as GLYATL2 in open-access papers:
GLYATL2 is named in the same sentence as 4 diseases in open-access papers, as found by Europe PMC text mining. Sharing a sentence is not in itself a finding about the gene and the disease. The quoted sentences say what the papers report.
breast carcinoma (2 papers, 2015 to 2018). "Noteworthy, the CM1 list revealed a set of probes for which little literature exists in relation to breast cancer subtypes: CDCA5, CCL15, COL17A1, GLYATL2, ROPN1, LINC00993 and C6orf211." (PMID 26132585, 2015).
prostate carcinoma (1 paper, 2025). A carcinoma that arises from epithelial cells of the prostate gland. "Genes such as ASCL1, WDFY4, GLYATL2, and EDIL3, which are upregulated in CRPC, likely drive the progression from primary prostate cancer to CRPC." (PMID 40165961, 2025).
cancer (2 papers, 2024 to 2025). A tumor composed of atypical neoplastic, often pleomorphic cells that invade other tissues. "Compared to primary cancer samples, genes such as GLYATL2, EDIL3, MEG3, FABP4, ASCL1, GRP, and WDFY4 were highly upregulated in CRPC, with statistically significant differences underscoring their potential roles in driving the castration-resistant phenotype." (PMID 40165961, 2025). "Among these model genes (FLNC, KLK6, PTGIS, PLAAT1 and GLYATL2), FLNC is an actin-binding protein that regulates the actin cytoskeleton in cells and is involved in cancer metastasis." (PMID 38363409, 2024).
GLYATL2 also shares sentences with these, for which no sentence is quoted: breast tumors (1 paper).